F9 (coagulation factor IX)
Description:
Factor IX is a vitamin K-dependent plasma protein that participates in the intrinsic pathway of blood coagulation by converting factor X to its active form in the presence of Ca(2+) ions, phospholipids, and factor VIIIa.
Synonyms: PTC; FIX; F9 p22; HEMB; P19; THPH8
Tractability: Small molecule: a structure with a bound ligand is known; a high-quality ligand is known; it belongs to a druggable protein family. Antibody: UniProt places it where antibodies can reach, with high confidence; its Gene Ontology location is reachable by antibodies, with high confidence; UniProt predicts a signal peptide or a membrane-spanning region. PROTAC: its protein half-life has been measured; a small molecule that binds it is known. Other modalities: an approved drug acts on it.
Target class: Serine protease; Enzyme; Serine protease PA clan; Serine protease S1A subfamily; Protease
Gene: Protein-coding gene on chromosome X (139,530,739 to 139,563,459, forward strand). Ensembl gene ENSG00000101981.
Subcellular location: Secreted
Pathways (Reactome):
Disease: Defective F9 activation; Defective F9 secretion; Defective F9 variant does not activate FX; Defective cofactor function of FVIIIa variant; Defective factor IX causes thrombophilia; Defective gamma-carboxylation of F9
Hemostasis: Amplification and propagation of coagulation cascade; FXIIa, PKa-dependent activation of coagulation pathway; Initiation of coagulation cascade; Regulation of clotting cascade
Metabolism of proteins: Gamma-carboxylation of protein precursors; Protein hydroxylation; Removal of aminoterminal propeptides from gamma-carboxylated proteins; Transport of gamma-carboxylated protein precursors from the endoplasmic reticulum to the Golgi apparatus
Gene Ontology:
Molecular function: calcium ion binding; endopeptidase activity; metal ion binding; protein binding; serine-type endopeptidase activity; peptidase activity
Biological process: blood coagulation; proteolysis; zymogen activation
Cellular component: extracellular exosome; extracellular matrix; extracellular region; endoplasmic reticulum lumen; Golgi lumen; plasma membrane
Gene-disease validity (ClinGen):
ClinGen rates the evidence that F9 causes each of these diseases.
hemophilia B (X-linked): Definitive. Hemophilia B is a form of hemophilia characterized by spontaneous or prolonged hemorrhages due to factor IX deficiency.
thrombophilia, X-linked, due to factor 9 defect (X-linked): Limited. A hemostatic disorder characterized by a tendency to thrombosis that has X-linked recessive inheritance, and can be caused by a gain-of-function mutation in the gene encoding factor IX (F9).
Homologues: Orthologues: chimpanzee F9 (98% identical), macaque F9 (97% identical), dog F9 (85% identical), pig F9 (85% identical), rabbit F9 (84% identical), mouse F9 (82% identical), rat F9 (82% identical), guinea pig F9 (80% identical), tropical clawed frog f9 (52% identical), zebrafish f9b (45% identical). Paralogues in human: F10 (44% identical), F7 (40% identical), C1R (26% identical), F12 (26% identical), HGFAC (26% identical), KLKB1 (25% identical), CFI (25% identical), C1S (24% identical), F11 (23% identical), C1RL (21% identical), PRSS55 (18% identical), CFD (18% identical), and 4 more.
Diseases named in the same sentence as F9 in open-access papers:
F9 is named in the same sentence as 101 diseases in open-access papers, as found by Europe PMC text mining. Sharing a sentence is not in itself a finding about the gene and the disease. The quoted sentences say what the papers report.
hemophilia B (219 papers, 2005 to 2026). "Hemophilia B is an X-linked bleeding disorder caused by inheritable mutations in the F9 gene that result in varying levels of deficiency of clotting factor IX activity." (PMID 40969675, 2025). "One approach has been successful in animal models, where CRISPR-Cas9 corrected the mutation in the Coagulation factor IX (FIX) gene associated with hemophilia B, restoring normal blood clotting." (PMID 41211267, 2025). "In 2022, the FDA approved the first gene therapy for hemophilia B, known as Hemgenix, which is based on an adeno-associated vector carrying the gene for coagulation factor IX." (PMID 40725041, 2025). "Hemophilia B is an X-linked recessive hereditary bleeding disorder characterized by reduced activity of coagulation factor IX." (PMID 40649878, 2025). "For example, Hemophilia B is a blood clotting disorder caused by mutations in the F9 gene, which encodes the clotting factor IX." (PMID 39985020, 2025). "Hemophilia, an X-linked recessive bleeding disorder, results from mutations in the F8 or F9 genes, leading to factor VIII (hemophilia A) or factor IX (hemophilia B) deficiency." (PMID 41153417, 2025). "The condition is primarily categorized into two clinical entities: hemophilia A, associated with mutations in the F8 gene encoding coagulation factor VIII, and hemophilia B, resulting from pathogenic variants in the F9 gene responsible for factor IX synthesis." (PMID 41153417, 2025). "Hemophilia B, an X-linked recessive bleeding disorder, arises from mutations in the F9 gene, leading to reduced production of functional coagulation factor IX (FIX) protein." (PMID 40499172, 2025). "Hemophilia B is a bleeding disorder caused by a mutated coagulation Factor IX (FIX) gene that results in insufficient FIX." (PMID 41476860, 2025). "For example, variants that disrupt a C/EBP or HNF4-binding element within the F9 gene promoter cause Hemophilia B Leyden, which is characterized by severe factor IX deficiency at birth that ameliorates after puberty." (PMID 38436667, 2024). "Examples include enhanced CD8+ T-cell responses to capsids, loss of F9 gene expression in AAV-transduced livers of hemophilia B patients, or inference with neuronal structure and function upon CNS gene transfer as recently shown in a mouse model." (PMID 39459842, 2024). "Hemophilia B is a clotting disorder caused by mutations in the human coagulation factor IX gene (hF9), which codes for a serine protease in the intrinsic pathway of the coagulation cascade." (PMID 39423215, 2024). "Hemophilia B is an X-linked bleeding disorder caused by a mutation in the gene responsible for encoding coagulation factor IX (FIX)." (PMID 39020429, 2024). "Hemophilia B is an X-linked bleeding disorder resulting from a mutation in the gene responsible for encoding coagulation factor IX (FIX)." (PMID 39020429, 2024). "Hemophilia B is a rare bleeding disorder in males, characterized by a deficiency in coagulation factor IX (FIX)." (PMID 39609856, 2024). "The disorder manifests in two primary forms: hemophilia A, caused by reduced levels of coagulation factor VIII (FVIII), and hemophilia B (also known as Christmas disease), caused by reduced levels of coagulation factor IX (FIX)." (PMID 39337384, 2024). "Hemophilia B is an X-linked bleeding disorder characterized by a deficiency in human coagulation factor IX, impacting approximately 1 in 25,000 individuals in the general population." (PMID 39598550, 2024). "Currently, the mainstay of disease management for hemophilia B, a hemorrhagic disease caused by a congenital deficiency or molecular abnormalities of blood coagulation factor IX (FIX), is prophylaxis using FIX concentrate." (PMID 36779089, 2023). "Hemophilia B is an X-linked congenital bleeding disorder caused by a deficiency of coagulation factor IX (FIX) clotting activity." (PMID 37790744, 2023).
hemophilia B (continued). "Hemophilia B is a rare X-linked recessive hereditary disease of the hemostasis system resulting from abnormalities in the F9 gene, which codes for blood coagulation factor IX and is located on the long arm of the X chromosome." (PMID 37445943, 2023). "Hemophilia B (HB) is an X-linked recessive disease caused by F9 gene mutation and functional coagulation factor IX (FIX) deficiency." (PMID 37240366, 2023). "Hemophilia B is a disease that can be completely cured by gene therapy, as it is caused by single defects in the F9 gene and has a wide therapeutic window." (PMID 37445943, 2023). "Another example is Factor IX (F9) which is associated with an X-linked bleeding disorder called Hemophilia B Leyden." (PMID 37497775, 2023). "Hemophilia B is a recessive hereditary disease, and manifestations result from coagulation factor IX deficiency." (PMID 36071731, 2022). "Mutations in the promoter region of the F9 gene often result in hemophilia B Leyden, which was first recognized in 1970." (PMID 35269902, 2022). "Among these blood coagulation disorders is hemophilia B (HB), a relatively rare condition affecting 1 in ∼50,000 live births, caused by mutations in the coagulation factor 9 gene (F9)." (PMID 36304295, 2022). "Hemophilia B patients are characterized by a deficiency of coagulation factor IX (FIX) resulting in bleeding, typically in joints and muscles." (PMID 33624121, 2021). "Hemophilia B (HB) is an X‐linked recessive inherited bleeding disorder caused by mutations in the F9 gene that lead to plasma factor IX deficiency." (PMID 32875744, 2020). "Loss-of-function mutations in the human coagulation factor 9 (F9) gene lead to hemophilia B. Here, we dissected the consequences and the pathomechanism of a non-coding mutation (c.2545A>G) in the F9 3’ untranslated region." (PMID 32267853, 2020). "Hemophilia A is caused by mutations of the F8 gene encoding coagulation factor VIII, while hemophilia B develops due to mutations of the F9 gene, which encodes coagulation factor IX." (PMID 32189222, 2020). "Disease-causing variants in the F9 gene cause complete or partial deficiency of the corresponding coagulation factor, ultimately leading to hemophilia B (OMIM:306900) of varying severity with an incidence of 1 in 25.000 births." (PMID 32267853, 2020). "Hemophilia B is a recessive X-linked disorder characterized by defective function or loss of the coagulation factor IX due to mutations in the gene F9, of which 40% cluster in exons 1–5." (PMID 31253089, 2019). "Significant progress has been made in treating hemophilia B (induced by F9 mutations) by adeno-associated virus (AAV)-based gene therapy due to the short length of the F9 protein (461 amino acids long)." (PMID 31843008, 2019). "Hemophilia B is an X‐linked recessive bleeding disorder caused by mutations in the F9 (OMIM 300746) on Xq27.1 resulting in reduced factor IX (FIX) activity." (PMID 30264515, 2018). "Hemophilia B is an X-linked bleeding disorder that results from a defect in the gene encoding coagulation factor IX (FIX), a serine protease that is critical for blood clotting." (PMID 29334995, 2018). "Severe to moderate hemophilia B, an X-linked hereditary deficiency of functionally active human coagulation factor IX (FIX), is characterized by spontaneous or traumatic bleeding episodes." (PMID 30003118, 2018). "Hemophilia B is the X-linked monogenetic disorder caused by the loss of functional coagulation factor IX (F.IX), resulting in a deficiency in the ability of blood to clot." (PMID 24460861, 2014). "Hemophilia B (HB) is an X-linked inherited disorder resulting from deficiency in the blood coagulation factor IX (F9) caused by mutation of the factor IX gene (F9; GenBank accession number K02402.1)." (PMID 25330515, 2014). "The features of coagulation factor IX (FIX) deficiency (Hemophilia B) make this disorder an ideal model to address this issue." (PMID 23994528, 2013).
hemophilia B (continued). "Hemophilia A is a deficiency in coagulation factor VIII (FVIII) and hemophilia B is a deficiency in coagulation factor IX (FIX)." (PMID 24883229, 2013). "Specifically, the example of hemophilia B illustrates how the coagulation factor IX (F9) is implicated in cellular senescence, suggesting that mutations in the F9 gene may reflect broader pathological processes." (PMID 40725041, 2025). "Hemophilia B is a disease that affects the human coagulation system, causing the absence or deficiency of coagulation factor IX, which may manifest itself in uncontrolled bleeding that is life-threatening to patients." (PMID 40178764, 2025). "Consequently, Hemophilia B Leyden is caused by a modular loss of F9 expression only within the prepubescent developmental stage." (PMID 38436667, 2024). "Silent variants in CFTR and F9 may decrease protein abundance through alterations to translation elongation, leading to cystic fibrosis and Hemophilia B, respectively." (PMID 38355921, 2024). "Hemophilia B, a rare genetic disease linked to the X chromosome, is characterized by mutations in the F9 gene, responsible for producing blood coagulation factor IX, also known as the Christmas factor." (PMID 39156766, 2024). "Hemophilia B is caused by an error in a gene called coagulation factor IX (F9)." (PMID 37076593, 2023). "Nevertheless, a pivotal study by Scalet and colleagues targeting several splicing mutations in the F9 gene causing Hemophilia B (Factor IX deficiency), proved that an ExSpeU1 can indeed rescue aberrant splicing caused by a variant located at the position +2 of the 5′ss." (PMID 37834063, 2023). "Hemophilia B is an X-linked congenital bleeding disorder caused by a deficiency of coagulation factor IX (FIX) clotting activity, which can manifest as bruising, spontaneous bleeding events, or excessive bleeding after an injury or surgery, particularly into muscles, joints, and soft tissues." (PMID 37790744, 2023). "Importantly, nonsense mutations in the F9 gene, which cause hemophilia B because of inactivation of coagulation factor IX, lead to appreciable readthrough and only a mild phenotype when the nonsense mutation is in a readthrough permissible UUGAC context." (PMID 36244451, 2022). "Hemophilia B is a bleeding disorder caused by a deficiency of coagulation factor IX (FIX)." (PMID 35207344, 2022). "More than 1000 mutations in the F9 gene have been identified in hemophilia B patients." (PMID 35269902, 2022). "Mutational screening of F9 gene in eleven clinically diagnosed Egyptian hemophilia-B patients and carrier mothers revealed four point mutations including two missense and two nonsense mutations that were correlating with phenotypic severity within the studied patients." (PMID 33999344, 2021). "While the largest set of in vivo genome editing trials was focused on treatment of cervical cancer, early use of in vivo ZFN gene editors was aimed to treat hemophilia B by replacing disease causing mutations in the F9 gene, which causes a deficiency of blood coagulation factor IX." (PMID 32207531, 2020). "For example, at least five reported cases of hemophilia A have been linked to germline MEIs that disrupted the coagulation factor VIII (F8) gene, and another six cases of hemophilia B have been linked to germline MEIs that disrupted the coagulation factor IX (F9) gene." (PMID 28855259, 2017). "Hemophilia B is caused by the absence or defect of an enzyme, coagulation factor IX (FIX)." (PMID 27766061, 2016). "The third SV was a 50bp tandem repeat insertion in the F9 gene, which is a coagulation factor associated with HEMB (Hemophilia B) and THPH8 (Thrombophilia, X-Linked, due to factor IX defect)." (PMID 34914762, 2021). "For hemophilia B, AAV-mediated delivery of hyperactive F9 transgenes—particularly the Padua variant (F9-R338L)—has demonstrated high levels of FIX activity with a single intravenous infusion." (PMID 40868273, 2025).
hemophilia B (continued). "The efficacy of hemophilia B (HB) replacement therapy is evaluated by coagulation factor IX (FIX) activity in plasma, although FIX bound to extravascular type IV collagen (Col4) also contributes to efficient hemostasis." (PMID 41022699, 2025). "Gene therapy for hemophilia B involves delivering a functional copy of the F9 gene into hepatocytes, the liver cells responsible for producing factor IX." (PMID 41153417, 2025). "Coagulation factor IX concentrates have greatly improved morbidity and mortality in hemophilia B since their introduction in the late 1960s." (PMID 40264735, 2025). "Hemophilia B (HB) patients are treated with recombinant coagulation factor IX (FIX) as replacement therapy." (PMID 41022699, 2025). "For hemophilia B, the standard model is mice with a knockout of the F9 gene (F9−/− line), which demonstrate a pathologically reduced plasma activity of coagulation factor IX (FIX) (<1% of normal)." (PMID 41155400, 2025). "They used minicircle DNA containing human coagulation factor IX, which is missing in patients with hemophilia type B, transfected the entire free flap with intraarterial perfusion and reimplanted the flap back into the same site." (PMID 39408659, 2024). "This strategy has been applied in the context of hemophilia B, to insert a corrective F9 cDNA into the second exon of the F9 gene using ZFN or CRISPR/Cas9 or the 3′end of the albumin safe harbor." (PMID 39246827, 2024). "Hemophilia B (HB, OMIM #306900; ICDX: D67) is an X‐linked recessive bleeding disorder caused by various mutations in the coagulation factor IX gene (F9, MIM #300746), resulting in a qualitative or quantitative deficiency of coagulation factor IX (FIX)." (PMID 39268837, 2024). "The vast majority of clinical studies on hemophilia B gene therapy are focused on the systemic delivery of a functional copy of the F9 gene using AAV vectors." (PMID 37445943, 2023). "We show that we are able to correct the genetic error in F9 in cells isolated from a patient with severe hemophilia B. We also show that we can fix the error in mice and that this increases levels of factor IX in the blood of the mice." (PMID 37076593, 2023). "Hemophilia Hemophilia is an inherited bleeding disorder that arises from a deficiency of coagulation factor (F)VIII in hemophilia A and Coagulation factor IX (FIX) in hemophilia B." (PMID 38017431, 2023). "Despite the recognition of F9-Padua as a game-changer in hemophilia B gene therapy, it is important to emphasize that there is a problem of assay discrepancies when evaluating post injection factor IX Padua levels." (PMID 37445943, 2023). "Coagulation factor IX (FIX) is a vitamin K dependent protein and its deficiency causes hemophilia B, an X-linked recessive bleeding disorder." (PMID 35269902, 2022). "For hemophilia B, a HC-Ad stabilizedthrough the Sleepy beauty transposase (SB) showed sustained expression of humancoagulation factor IX for more than six months in mice." (PMID 36206378, 2022). "Aiming at developing a highly efficient gene therapy for hemophilia B, we constructed a promoterless donor vector containing the human coagulation factor IX cDNA, carrying the V86A, E277A, and R338L-Padua hyperactive mutations." (PMID 35359664, 2022). "Hemophilia A is treated with human plasma coagulation factor VIII (FVIII) replacement therapy and Hemophilia B with coagulation factor IX, which is purified from prothrombin complex concentrate (PCC)." (PMID 36297304, 2022). "These hemophilia B mice have a deletion of endogenous F9 gene and therefore lack tolerance to FIX antigen." (PMID 34135899, 2021). "Historically we have observed that the hemophilia B mice on a BALB/c background are less responsive to FIX protein therapy compared to mice on the C3H/HeJ background with an identical F9 gene deletion." (PMID 32670285, 2020).